VPS9D1-AS1 (VPS9D1 antisense RNA 1)
Synonyms: MYU; FAISL
Gene: Long non-coding RNA gene on chromosome 16 (89,711,856 to 89,718,165, forward strand). Ensembl gene ENSG00000261373.
Diseases named in the same sentence as VPS9D1-AS1 in open-access papers:
VPS9D1-AS1 is named in the same sentence as 15 diseases in open-access papers, as found by Europe PMC text mining. Sharing a sentence is not in itself a finding about the gene and the disease. The quoted sentences say what the papers report.
prostate carcinoma (2 papers, 2020 to 2024). A carcinoma that arises from epithelial cells of the prostate gland. "LncRNA VPS9D1 antisense RNA 1 (VPS9D1-AS1) is indicated to promote prostate cancer cell proliferation by targeting miR-184/c-Myc pathway and to serve as a prognosis predictor in non-small cell lung cancer." (PMID 32808668, 2020). "For examples, VPS9D1-AS1 (also called MYU) boosts prostate cancer cell proliferation by mediation of miR-184c-Myc axis; increased expression of VPS9D1-AS1 predicts dismal prognosis in non-small cell lung cancer." (PMID 32808668, 2020).
cancer (4 papers, 2021 to 2024). A tumor composed of atypical neoplastic, often pleomorphic cells that invade other tissues. "To determine whether MYU (VPS9D1-AS1) might be involved in angiogenesis during cancer, we examined its expression levels in different tumor tissues compared with the corresponding normal tissues by interrogating the RNA-seq datasets of 22 common malignancies from The Cancer Genome Atlas database." (PMID 39056780, 2024).
VPS9D1-AS1 also shares sentences with these, for which no sentence is quoted: colon cancer (4 papers); tumor (3); lung adenocarcinoma (2); acute lymphoblastic leukemia (1); bladder carcinoma (1); breast carcinoma (1); colorectal cancer (1); head‐neck squamous cell carcinoma (1); non-small cell lung carcinoma (1); ovarian carcinoma (1); paraganglioma (1); pheochromocytoma (1); triple-negative breast carcinoma (1).